OSR1 (odd-skipped related transcription factor 1)
Description:
Transcription factor that plays a role in the regulation of embryonic heart and urogenital development.
Synonyms: ODD
Tractability: Small molecule: a high-quality ligand is known. PROTAC: ubiquitination databases record sites on it; a small molecule that binds it is known.
Target class: Transcription factor
Gene: Protein-coding gene on chromosome 2 (19,351,485 to 19,359,486, reverse strand). Ensembl gene ENSG00000143867.
Subcellular location: Nucleus
Pathways (Reactome):
Developmental Biology: Formation of intermediate mesoderm; Formation of the nephric duct
Gene Ontology:
Molecular function: sequence-specific double-stranded DNA binding; DNA-binding transcription factor activity, RNA polymerase II-specific; RNA polymerase II transcription regulatory region sequence-specific DNA binding; transporter inhibitor activity
Biological process: negative regulation of sodium ion transmembrane transport; negative regulation of transmembrane transport; positive regulation of gastrulation; pronephros development; cell differentiation; cell proliferation involved in kidney development; chondrocyte differentiation; embryonic digit morphogenesis; embryonic forelimb morphogenesis; embryonic hindlimb morphogenesis; embryonic skeletal joint development; embryonic skeletal joint morphogenesis; embryonic skeletal limb joint morphogenesis; heart development; mesangial cell development; mesonephric duct morphogenesis; mesonephros development; metanephric cap mesenchymal cell proliferation involved in metanephros development; metanephric epithelium development; metanephric glomerulus vasculature development; metanephric interstitial fibroblast development; metanephric mesenchymal cell differentiation; metanephric mesenchyme development; metanephric mesenchyme morphogenesis; metanephric nephron tubule development; and 24 more
Cellular component: nucleus; cell cortex; chromatin; cytosol
Genetic constraint (gnomAD): Loss-of-function variants: 3 observed, 16.62 expected, observed/expected ratio (o/e) 0.18, 90% interval 0.081 to 0.47. The upper end of that interval is the gene's LOEUF score, 0.47, which puts it in group 2 of 6, group 1 being the genes least tolerant of losing a copy. Missense variants: 271 observed, 370.22 expected, observed/expected ratio (o/e) 0.73, 90% interval 0.66 to 0.81. Synonymous variants: 166 observed, 163.26 expected, observed/expected ratio (o/e) 1.02, 90% interval 0.89 to 1.16.
Gene-disease validity (ClinGen):
ClinGen rates the evidence that OSR1 causes each of these diseases.
congenital heart disease (autosomal dominant): Disputed. A heart disease that is present at birth.
Homologues: Orthologues: chimpanzee OSR1 (99% identical), macaque OSR1 (99% identical), mouse Osr1 (98% identical), pig OSR1 (98% identical), rabbit OSR1 (98% identical), rat Osr1 (98% identical), dog OSR1 (97% identical), guinea pig OSR1 (97% identical), tropical clawed frog osr1 (85% identical), zebrafish osr1 (76% identical), Caenorhabditis elegans odd-1 (33% identical), Drosophila melanogaster drm (15% identical). Paralogues in human: OSR2 (67% identical).
Diseases named in the same sentence as OSR1 in open-access papers:
OSR1 is named in the same sentence as 88 diseases in open-access papers, as found by Europe PMC text mining. Sharing a sentence is not in itself a finding about the gene and the disease. The quoted sentences say what the papers report.
breast carcinoma (14 papers, 2020 to 2025). "WNK kinases and the downstream SPAK/OSR1 kinases are implicated in the migration, proliferation and metastasis of human gliomas, hepatocellular carcinoma, breast cancer and colon cancer." (PMID 40643468, 2025). "In conclusion, the study demonstrated that elevated OSR1 expression is associated with reduced proliferation of breast cancer cells and enhanced immune cell infiltration within the TME." (PMID 40692711, 2025). "In breast cancer, elevated OSR1 expression has been associated with unfavorable prognoses and enhanced metastatic potential of endothelial cells, potentially mediated by altered TGF-β1 secretion through phosphorylation of the Smad2/3 linker region." (PMID 40692711, 2025). "OXSR1 encodes a serine–threonine protein kinase, and studies have shown that high OSR1 expression causes an increase in deaths specifically attributed to breast cancer and is related to an increase in lymph node metastasis." (PMID 36414988, 2022). "The most-reported associations for CpG sites within the OSR1 gene are for breast cancer (6 associations), and atherosclerosis (5 associations)." (PMID 35836279, 2022). "Notably, reduced OSR1 expression is associated with poorer survival outcomes in breast cancer, indicating its potential as an independent prognostic biomarker." (PMID 40692711, 2025). "Similarly, high expression of Odd-skipped related transcription factor 1 (OSR1) has been used as a predictive biomarker for poor prognosis and linked to lymph node metastases in breast cancer." (PMID 38694815, 2024). "Overall, OSR1 overexpression is strongly associated with tumor aggressiveness in breast cancer." (PMID 37627077, 2023). "OSR1 expression was significantly reduced in breast cancer tissues and correlated negatively with breast cancer progression." (PMID 40692711, 2025). "This study not only identifies OSR1 as a methylation-driven gene but also delineates its functional and biological relevance in breast cancer." (PMID 40692711, 2025). "The results demonstrated significantly reduced OSR1 expression and elevated methylation levels in breast cancer tissues compared to normal counterparts, suggesting that OSR1 functions as a methylation-driven tumor suppressor gene." (PMID 40692711, 2025). "The protein kinase OSR1 has been highlighted as a biomarker for a poor prognosis in breast cancer (BC) patients." (PMID 40109757, 2025). "To further validate the potential clinical significance of these methylation-driven genes, we performed survival analysis and found that OSR1 expression was clinically relevant to the prognosis of breast cancer patients." (PMID 40692711, 2025). "OSR1 expression was significantly downregulated in breast cancer tissues relative to normal breast tissues (p < 0.001), a trend that was further validated in 113 paired tumor-normal samples (p < 0.001)." (PMID 40692711, 2025). "In the present study, OSR1 was identified as a methylation-driven gene in breast cancer through integrated analysis of the TCGA and GEO datasets." (PMID 40692711, 2025). "Differential expression analysis using the Wilcoxon rank-sum test revealed significantly reduced OSR1 expression in breast cancer tissues compared to normal counterparts." (PMID 40692711, 2025). "Despite these insights, the functional role of OSR1 in breast cancer remains insufficiently characterized." (PMID 40692711, 2025). "Both in vitro and in vivo studies demonstrated that OSR1 overexpression markedly suppressed breast cancer cell proliferation and migration." (PMID 40692711, 2025). "In this study, OSR1 expression and methylation status in breast cancer were analyzed using TCGA datasets." (PMID 40692711, 2025). "Nonetheless, due to the inherent heterogeneity of breast cancer, the oncogenic relevance, clinical implications, and immunological context of OSR1 dysregulation remain incompletely characterized." (PMID 40692711, 2025).
breast carcinoma (continued). "Conversely, OSR1 has also been identified as a tumour suppressor gene in breast cancer, where reduced expression promotes breast cancer proliferation and invasion." (PMID 38694815, 2024). "OSR1 mRNA and protein levels in human breast cancer cell lines are significantly upregulated and the presence of phosphorylated OSR1 in breast cancer patients was identified as an independent indicator of poor prognosis." (PMID 37627077, 2023). "OSR1 downregulation in breast cancer negatively correlates with lymph node metastasis and ER expression." (PMID 37642735, 2023). "Furthermore, in vitro Transwell migration assays revealed that OSR1 overexpression markedly suppressed the migratory potential of breast cancer cells." (PMID 40692711, 2025). "However, the precise molecular mechanisms by which OSR1 contributes to breast cancer biology remain to be elucidated." (PMID 40692711, 2025). "OSR1 has been found as overexpressed in various types of cancer, including breast cancer." (PMID 37627077, 2023). "OSR1 downregulates Wnt signaling pathway activation in breast cancer." (PMID 37642735, 2023). "Indeed, eliminating OSR1 in breast cancer cells prevented these phenotypic changes." (PMID 37627077, 2023). "Interestingly, eight genes (ID4, LTBP4, GPM6B, RGMA, EFCAB1, ALX4, OSR1 and PPARA) were confirmed to be down-expressed in breast cancer tissues, and associated with the overall survival time of breast cancer patients, as high expression of these genes correlate with an improved prognosis." (PMID 32650755, 2020). "In the EMT model of breast cancer cells, circSCYL2 and its target gene OSR1, which interacts with the TGF pathway, were dysregulated, but upregulating circSCYL2 in breast cancer cells inhibited cell migration and invasion." (PMID 37243750, 2023). "The potential target genes of miR-1908-3p in breast cancer included ID4, LTBP4, GPM6B, RGMA, EFCAB1, ALX4, OSR1 and PPARA." (PMID 32650755, 2020). "In our recent study, we found elevated phospho-OSR1 in bone metastatic cells, suggesting that increased WNK activity may be a feature of breast cancers that can metastasize to multiple sites." (PMID 35813203, 2022). "Based on these findings, a potential miR-1908-3p-mRNA regulatory network, miR-1908-3P-ID4/ LTBP4/ GPM6B/ RGMA/ EFCAB1/ ALX4/ OSR1/ PPARA, contributing to breast cancer onset and progression could be established." (PMID 32650755, 2020). "Consistent with this, it has recently been proposed that OSR1 depletion in MDA-MB-231 cells displays a decrease in expression of EMT transcription factors Twist1, Snail, and Slug at mRNA and protein levels, resulting in reduced invasion of breast cancer cells in vitro and in vivo." (PMID 35813203, 2022). "The inclusion of GREB1, OSR1, and FAM83D, which are not in the PAM50 gene signature, highlights the potential of our integrative approach to reveal prognostic markers related to breast cancer intrinsic subtypes." (PMID 39452108, 2024). "We found that depletion of OSR1 also reduced migration of breast cancer cells; however, inhibition of NKCC1 was not as effective as OSR1 depletion in slowing migration." (PMID 35813203, 2022).
Hypertension (14 papers, 2014 to 2025). The presence of chronic increased pressure in the systemic arterial system. "In particular, the decrease in Prdx5 by Ang II in DCT increased the activity of the WNK4-SPAK/OSR1-NCC axis associated with the development of hypertension." (PMID 39857434, 2025). "This stabilization of WNKs presumably caused activation of the WNK/SPAK/OSR1 kinase cascade and hypertension through excess activity of the WNK/SPAK/NCC pathway." (PMID 27815594, 2017). "This presumably caused activation of the WNK/SPAK/OSR1 kinase cascade and hypertension through excess activity of the WNK/SPAK/NCC pathway." (PMID 27815594, 2017). "Activation of the WNK4-SPAK/OSR1-NCC signaling axis is one of the master signal pathways responsible for hypertension." (PMID 39857434, 2025). "While this review focused on the WNK-centric pathomechanisms in hypertension, we also surveyed the small molecule inhibitors that target the WNK-SPAK/OSR1 axis in the context of hypertension." (PMID 36140271, 2022). "Mutations in WNK1 result in dysregulation of the WNK1-SPAK/OSR1 pathway and cause pseudohypoaldosteronism type II (PHAII), a form of hypertension." (PMID 36151370, 2022). "CCCs are also involved in hypothalamic signaling in hypertension and the mutations in the regulatory CUL3/KLHL3-WNK-SPAK/OSR1 pathway contribute to the pathology of FHHt." (PMID 33066544, 2020). "There is increasing interest in targeting the WNK-SPAK/OSR1-signalling pathway as a new therapeutic strategy to treat hypertension." (PMID 25994507, 2015). "Next, we determined whether the deletion of Prdx5 was related to the expression and activity of NCC, which has been shown to cause hypertension, and whether the efficacy of Prdx5 was dependent on the WNK-SPAK/OSR1 pathway, the master activator of NCCs." (PMID 39857434, 2025). "The many roles of the WNK-SPAK/OSR1-CCC pathway which include cell volume homeostasis, epithelial transport, and GABA signaling are associated with an array of pathologies which include essential hypertension, cerebral edema, anemia, and neuropathic pain." (PMID 33513812, 2021). "Although there are limitations in the development of therapeutics for hypertension, the possibility of a therapeutic strategy targeting the regulatory pathway, WNK4-SPAK/OSR1, as a master activator of NCC is promising." (PMID 39857434, 2025). "Mutations in the WNK1 gene increase L-WNK1 expression in the distal tubule, leading to overstimulation of the WNK-SPAK/OSR1-NCC pathway, which results in enhanced NaCl reabsorption and contributes to hypertension." (PMID 39859138, 2025). "Gene mutations in WNK1 and WNK4 result in over-activation of the WNK-SPAK/OSR1 pathway, therefore increased phosphorylation and activation of NCC occurs in the kidney, resulting in hypertension." (PMID 33066544, 2020). "This, in turn, would be predicted to lead to overactivation of SPAK/OSR1 and the NCC/NKCC2 ion co-transporters, and consequently, increased salt retention leading to hypertension." (PMID 24641320, 2014). "Therefore, the WNK-SPAK/OSR1-NCC pathway is overactivated, and NaCl reabsorption is increased, leading to hypertension." (PMID 37779914, 2023). "Researchers have made great effects in elaborating inhibitors against WNKs or SPAK/OSR1 to treat hypertension, for example, WNKs kinase inhibitor: WNK463, PP121; SPAK/OSR1 inhibitors: STOCK1S-14279 and Closantel, Rafoxanide, Verteporfin, STOCK1S-50699, and STOCK2S-26016." (PMID 33266310, 2020). "Indeed, current research is focused on identifying novel targets within the WNK-SPAK/OSR1 pathway for use in FHHt and potentially non-Mendelian forms of hypertension." (PMID 33066544, 2020).
glioma (9 papers, 2014 to 2025). A benign or malignant brain and spinal cord tumor that arises from glial cells (astrocytes, oligodendrocytes, ependymal cells). "Pharmacological inhibition of NKCC1 significantly reduces glioma cell migration after TMZ treatment with drugs that inhibit elements of the WNK1/OSR1/NKCC1 signaling pathway." (PMID 40725030, 2025). "In gliomas, reduced OSR1 expression has been shown to influence cell migration by modulating the phosphorylation state of the Na+-K+-2Cl–cotransporter isoform 1 (NKCC1), subsequently altering intracellular Cl−and K+ concentrations." (PMID 40692711, 2025). "Small interfering RNA‐mediated WNK1 or OSR1 knockdown reduced glioma migration by eliminating NKCC1‐regulated phosphorylation activation." (PMID 37786890, 2022). "Reduce K+ and Cl− concentrations intracellularly, increase NKCC1, WNK1, and OSR1 phosphorylation, and enhance glioma migration." (PMID 37786890, 2022). "Taken together, these novel findings suggest that combination of TMZ-mediated chemotherapy with inhibition of the WNK1/OSR1/NKCC1 signaling pathway presents a new strategy for improving glioma treatment." (PMID 24555568, 2014). "Expression of NKCC1 and its upstream kinases With-No-K (Lysine) kinase 1 (WNK1) and oxidative stress-responsive kinase-1 (OSR1) in different human glioma cell lines and glioma specimens were detected by western blotting and immunostaining." (PMID 24555568, 2014). "Pharmacological inhibition of NKCC1 with its potent inhibitor BMT or siRNA knockdown of WNK1 or OSR1 significantly decreases glioma cell migration after TMZ treatment." (PMID 24555568, 2014). "We report here that WNK1 and OSR1 are the dominant upstream regulatory kinases of NKCC1 in glioma cells." (PMID 24555568, 2014). "Small interfering RNA (siRNA)-mediated knockdown of WNK1 or OSR1 was used to explore their roles in regulation of NKCC1 activity in glioma cells." (PMID 24555568, 2014). "Taken together, these findings suggest that the WNK1/OSR1/NKCC1 signal pathway may be important in pathogenesis of glioma." (PMID 24555568, 2014). "Moreover, the WNK1/OSR1/NKCC1 signaling pathway plays an important role in glioma migration and is stimulated by TMZ." (PMID 24555568, 2014). "Interestingly, the basal expression of p-OSR1 remained high in both primary glioma cell lines as well as in U87 (p < 0.05)." (PMID 24555568, 2014). "In the activation of the WNK pathway in gliomas, there is a direct relationship between cell volume preservation by the WNK-SPAK/OSR1 pathway components and tumor aggressiveness." (PMID 40643468, 2025). "Some studies have shown that the inhibition of WNK kinase and OSR1 kinase upstream of NKCC1 can also reduce intracellular chloride concentration and inhibit the process of RVI in glioma cells, inhibiting cell invasion." (PMID 32211242, 2020). "The WNK1/SPAK/OSR1 signaling pathway is a well-studied upstream regulatory component of NKCC1, and it has been reported that WNK1 and OSR1 regulate the activation and phosphorylation of NKCC1 in human glioma cells." (PMID 29029515, 2017). "First, we characterized expression of WNK1, SPAK, OSR1, and NKCC1 protein in human neural stem cells (NSC), human astrocytes (HA), primary glioma cells (GC#99 and GC#22), and GBM cell line U87." (PMID 24555568, 2014). "siRNA-mediated knockdown of WNK1 or OSR1 reduces intracellular K+ and Cl- content and RVI in glioma cells by abolishing NKCC1 regulatory phospho-activation." (PMID 24555568, 2014). "We show that compared to human neural stem cells and astrocytes, human glioma cells exhibit robust increases in the activation and phosphorylation of NKCC1 and its two upstream regulatory kinases, WNK1 and OSR1." (PMID 24555568, 2014). "WNK1/OSR1 kinases function in stimulation of NKCC1 activity to maintain intracellular K+ and Cl- and cell volume homeostasis, which is important for glioma migration." (PMID 24555568, 2014). "TMZ treatment activates the WNK1/OSR1/NKCC1 pathway, thus increasing the glioma migration." (PMID 36292952, 2022).
glioma (continued). "Together, our data show a novel role for the WNK1/OSR1/NKCC1 pathway in basal and TMZ-induced glioma migration, and suggest that glioma treatment with TMZ might be improved by drugs that inhibit elements of the WNK1/OSR1/NKCC1 signaling pathway." (PMID 24555568, 2014). "We speculate that WNK1/OSR1-mediated phosphorylation of NKCC1 protein may alter its interaction with ERM complex and promote glioma cell migration." (PMID 24555568, 2014). "Unexpectedly, TMZ activates the WNK1/OSR1/NKCC1 signaling pathway and enhances glioma migration." (PMID 24555568, 2014). "TMZ may activate the WNK1/OSR1/NKCC1 signaling pathway and enhance glioma cell migration." (PMID 40725030, 2025). "We previously found that TMZ stimulated NKCC1 protein upregulation and activation in human primary glioma cells (GC#99 and GC#22) through With-No-K (lysine) kinase 1 (WNK1) and oxidative stress-responsive kinase 1 (OSR1) signaling pathway." (PMID 32848856, 2020). "In the present study, we investigated whether WNK1-SPAK/OSR1 signaling pathway regulates NKCC1 activity in GCs and whether this signaling pathway is involved in regulation of glioma migration, with and without chemotherapeutic treatment." (PMID 24555568, 2014).